SGPP2 (sphingosine-1-phosphate phosphatase 2)
Description:
Has specific phosphohydrolase activity towards sphingoid base 1-phosphates. Has high phosphohydrolase activity against dihydrosphingosine-1-phosphate and sphingosine-1-phosphate (S1P) in vitro. Sphingosine-1-phosphate phosphatase activity is needed for efficient recycling of sphingosine into the sphingolipid synthesis pathway (By similarity). May play a role in attenuating intracellular sphingosine 1-phosphate (S1P) signaling. May play a role in pro-inflammatory signaling. Plays a role in the regulation of pancreatic islet beta-cell endoplasmic reticulum stress and proliferation (By similarity).
Synonyms: SPPase2; Spp2; FLJ39004
Tractability: Antibody: UniProt predicts a signal peptide or a membrane-spanning region.
Gene: Protein-coding gene on chromosome 2 (222,424,511 to 222,562,621, forward strand). Ensembl gene ENSG00000163082.
Subcellular location: Endoplasmic reticulum membrane
Pathways (Reactome):
Metabolism: Sphingolipid catabolism
Gene Ontology:
Molecular function: dihydrosphingosine-1-phosphate phosphatase activity; sphingosine-1-phosphate phosphatase activity
Biological process: sphingosine metabolic process; phospholipid dephosphorylation; regulation of type B pancreatic cell proliferation; sphingolipid catabolic process
Cellular component: endoplasmic reticulum; endoplasmic reticulum membrane
Genetic constraint (gnomAD): Loss-of-function variants: 30 observed, 33.06 expected, observed/expected ratio (o/e) 0.91, 90% interval 0.68 to 1.23. The upper end of that interval is the gene's LOEUF score, 1.23, which puts it in group 5 of 6, group 1 being the genes least tolerant of losing a copy. Missense variants: 456 observed, 490.13 expected, observed/expected ratio (o/e) 0.93, 90% interval 0.86 to 1. Synonymous variants: 233 observed, 205.24 expected, observed/expected ratio (o/e) 1.14, 90% interval 1.02 to 1.26.
Homologues: Orthologues: chimpanzee SGPP2 (99% identical), macaque SGPP2 (97% identical), pig SGPP2 (91% identical), rabbit SGPP2 (90% identical), mouse Sgpp2 (80% identical), rat Sgpp2 (80% identical), guinea pig SGPP2 (80% identical), dog SGPP2 (69% identical), tropical clawed frog sgpp2 (53% identical), Caenorhabditis elegans T13C5.6 (8% identical), Drosophila melanogaster CG31717 (7% identical). Paralogues in human: SGPP1 (36% identical), PLPP7 (12% identical), PLPP6 (12% identical).
Diseases named in the same sentence as SGPP2 in open-access papers:
SGPP2 is named in the same sentence as 34 diseases in open-access papers, as found by Europe PMC text mining. Sharing a sentence is not in itself a finding about the gene and the disease. The quoted sentences say what the papers report.
gastric cancer (4 papers, 2021 to 2025). A primary or metastatic malignant neoplasm involving the stomach. "It has been reported that Nudix hydrolase 21 promotes tumor growth and metastasis through modulating SGPP2 in gastric cancer." (PMID 34956309, 2021). "For downstream mechanisms, SGPP2 was identified to be positively regulated by NUDT21 in gastric cancer cells." (PMID 34660260, 2021). "Therefore, NUDT21 stimulated cell proliferation and metastasis in gastric cancer cells through specific regulation of SGPP2." (PMID 34660260, 2021). "In addition, we examined the role of SGPP2 in gastric cancer cells in vivo." (PMID 34660260, 2021). "Therefore, NUDT21 positively regulated the expression of SGPP2 in human gastric cancer cells." (PMID 34660260, 2021). "Therefore, Bcl-2 and CCNE1 might contribute to the tumor promoting role of the NUDT21/SGPP2 pathway in gastric cancer cells." (PMID 34660260, 2021). "Therefore, SGPP2 mediated the tumor promoting role of NUDT21 in gastric cancer cells." (PMID 34660260, 2021). "SGPP2 was positively regulated by NUDT21 and mediated the oncogenic role of NUDT21 in gastric cancer cells." (PMID 34660260, 2021). "We herein reported that SGPP2 was specifically regulated by NUDT21, promoting gastric cancer cell proliferation and metastasis, and mediated the oncogenic role of NUDT21 in gastric cancer cells." (PMID 34660260, 2021). "Through high throughput RNA-sequencing, SGPP2 was identified to be positively regulated by NUDT21 and mediated the tumor promoting role of NUDT21 in gastric cancer cells." (PMID 34660260, 2021). "Through high throughput RNA-sequencing, an important oncogene SGPP2 (sphingosine-1-phosphate phosphatase 2, also known as SPP2) was found to be positively regulated by NUDT21 and mediated the tumor promoting role of NUDT21 in gastric cancer cells." (PMID 34660260, 2021).
glioma (4 papers, 2014 to 2021). A benign or malignant brain and spinal cord tumor that arises from glial cells (astrocytes, oligodendrocytes, ependymal cells). "Our own study on malignant gliomas demonstrated that SGPP2, but not SGPP1, was strongly downregulated as a function of glioma malignancy, and that levels of SGPP2 were inversely correlated with S1P." (PMID 24970218, 2014).
colitis (2 papers, 2019 to 2021). Inflammation of the colon. "In contrast, the degradation of S1P in colon epithelial cells by sphingosine-1-phosphate phosphatase 2 promotes disruption of mucosal integrity and enhances DSS-induced colitis." (PMID 31277430, 2019).
diabetes (2 papers, 2014 to 2021). "The level of SPL was decreased 1.6 fold and the levels of SGPP1 and SGPP2 were also decreased 4.8 fold and 15.7 fold separately in diabetes compared with control subjects." (PMID 24751283, 2014).
glioblastoma (2 papers, 2015 to 2021). The most malignant astrocytic tumor (WHO grade IV). "In addition, increased S1P in glioblastoma multiforme tissues is associated with increased SPHK1 and decreased expression of S1P phosphatase (SGPP2)." (PMID 26493335, 2015).
psoriasis (2 papers, 2015 to 2024). An autoimmune condition characterized by red, well-delineated plaques with silvery scales that are usually on the extensor surfaces and scalp. "Upregulation of SGPP2 has been detected in samples of skin lesions from patients with psoriasis, a chronic inflammatory skin disease." (PMID 26556954, 2015). "Given that S1P is downregulated in skin inflammatory conditions, such as atopic dermatitis, SGPP2 is upregulated in psoriasis, and SGPP2 is involved in inflammatory signaling in immune and endothelial cells, we hypothesized that SGPP2 contributes to inflammatory pathways in the skin." (PMID 39194756, 2024).
ulcerative colitis (2 papers, 2017 to 2025). An inflammatory bowel disease involving the mucosal surface of the large intestine and rectum. "For example, in the inflamed colonic mucosa of patients with ulcerative colitis, the expression level of SGPP2 was significantly higher than that of normal tissue." (PMID 41408309, 2025). "Although little is known about the physiological function of SGPPs, it has been reported that SGPP2 promotes disruption of mucosal integrity and contributes to ulcerative colitis in mice and humans, being a therapeutic target in IBD." (PMID 28300788, 2017).
atherosclerosis (1 paper, 2022). A disease characterized by the build-up of fatty material and calcium deposition in the arterial wall resulting in partial or complete occlusion of the arterial lumen. "The results of previous studies suggest that the SGPP2 gene may be involved in the onset and progress of atherosclerosis." (PMID 35795669, 2022). "To identify robust biomarkers that may serve as early warning signals of AMI, we analyzed the common genes (overlapping genes) between differentially expressed gene sets and DNB gene sets and identified the SGPP2 genes that may play key roles in the process of atherosclerosis progression." (PMID 35795669, 2022).
breast invasive carcinoma (1 paper, 2021). "Expression of the second isoform of SGPP i.e., SGPP2, was not significantly different in breast invasive carcinoma compared to normal tissue." (PMID 34235182, 2021).
heart failure (1 paper, 2023). Inability of the heart to pump blood at an adequate rate to meet tissue metabolic requirements. "Conversely, SGPP2 was highly expressed in normal samples and may serve as a protective gene against heart failure." (PMID 38250028, 2023). "However, only SDSL showed an AUC value greater than 0.7 in the test set, whereas EGFL7, SMTNL2, MFAP4, TAGLN, SGPP2 and SMTNL2 showed AUC values greater than 0.5, so SDSL may be a high risk factor in patients with heart failure." (PMID 38250028, 2023).
hepatocellular carcinoma (1 paper, 2021). A malignant tumor that arises from hepatocytes. "The 5-methylcytosine correlation score composed of SGPP2 and 6 other genes was reported to be significantly related to the prognosis of hepatocellular carcinoma." (PMID 34660260, 2021).
inflammatory bowel disease (1 paper, 2025). A spectrum of small and large bowel inflammatory diseases of unknown etiology. "Existing literature suggests that SGPP2 gene may function as a novel vitamin D-responsive gene associated with lung function and may serve as a potential immune regulator in inflammatory bowel disease (IBD)." (PMID 41141997, 2025).
Insulin resistance (1 paper, 2019). Increased resistance towards insulin, that is, diminished effectiveness of insulin in reducing blood glucose levels. "SGPP2, IGSF3, and VSIG2 are novel biomarkers for the development of insulin resistance." (PMID 30678306, 2019).
liver fibrosis (1 paper, 2025). "In contrast, Ppp2r2b, Sgpp2 (P < 0.0001), and Oprd1 (P < 0.001) were significantly upregulated in the WD liver fibrosis model." (PMID 40557038, 2025).
melanoma (1 paper, 2021). A malignant, usually aggressive tumor composed of atypical, neoplastic melanocytes. "In the anti-CTLA-4 cohort, higher SGPP2 expression in melanoma patients was associated with a better therapeutic benefit." (PMID 35004676, 2021).
skin aging (1 paper, 2024). The gradual irreversible changes in structure of skin that occur as a result of the passage of time.. "This study highlights the potential of SGPP2 gene modulation as a therapeutic strategy to combat skin aging, particularly facial wrinkles, by targeting the underlying inflammatory processes." (PMID 39194756, 2024). "By regulating SGPP2 expression and activity, effective control of inflammatory mediators is expected, alleviating skin aging and promoting skin health." (PMID 39194756, 2024).
systemic lupus erythematosus (1 paper, 2021). An autoimmune multi-organ disease typically associated with vasculopathy and autoantibody production. "Sgpp2 can be induced during inflammatory responses, and its abnormal expression enhances B cell- and macrophage-mediated inflammation in patients and mice with systemic lupus erythematosus." (PMID 33601337, 2021).
tumor (10 papers, 2016 to 2025). "YAP phosphorylation and activation of the sphingolipid metabolic enzyme SGPP2 jointly mediate tumor metabolic adaptation; whilst the sphingolipid metabolic enzyme CERK promotes drug resistance in ER+ BC." (PMID 41415282, 2025). "The qRT-PCR results suggested that the expression of SGPP2 was significantly elevated in tumor tissue specimens, while the expression of SRD5A2 was significantly increased in normal tissue." (PMID 36106334, 2022). "The findings also showed that the mRNA expression of SGPP2 was higher in tumor tissues, whereas the mRNA expression of SRD5A2 was higher in normal tissues." (PMID 36106334, 2022). "SGPP2 was found to play multiple roles including tumor progression and inflammatory responses." (PMID 35097000, 2021). "Therefore, Bcl-2 and CCNE1 might contribute to the tumor promoting role of the NUDT21/SGPP2 pathway." (PMID 34660260, 2021). "Therefore, we further confirmed whether the upregulated BAMBI, SLC26A9, SGPP2, and TMC8 genes could be used as a gene signature for EBVaCAs by determining the expression levels of these four genes in cell lines and tumor tissues by qRT-PCR." (PMID 35008199, 2021). "Similarly, the expression of SLC26A9 and TMC8, but not BAMBI or SGPP2, was significantly upregulated in EBV-positive tumor tissues compared with that in EBV-negative tumor tissues." (PMID 35008199, 2021). "However, SLC26A9 and TMC8, but not BAMBI and SGPP2, were significantly upregulated in EBV-positive tumor tissues compared to EBV-negative tumor tissues." (PMID 35008199, 2021).
cancer (7 papers, 2010 to 2020). A tumor composed of atypical neoplastic, often pleomorphic cells that invade other tissues. "Together with our data, these observations suggest that increased SPHK1 and decreased SGPL1 or SGPP2 may be a relatively common pathogenic mechanism that could also be involved with therapy resistance in several cancer types." (PMID 26493335, 2015). "S1P degradation enzymes, SGPP1, SGPP2 andSGPL1 are enzymes that metabolize S1P in the cell and their importance comes from their role in controlling the levels of S1P in the cell, excessive concentrations of which are detrimental to cell fate and functions as well as drug resistance and cancer." (PMID 26485657, 2015). "For examples, RSAD2, involved in antiviral defense, has not been reported as being related to cancer, as well as SGPP2, known to be involved in pro-inflammatory signaling, and CST4." (PMID 21060876, 2010). "Yet, data on the role of GSTM5, PDE6B, SGPP2, PDE1B, DGKB, and PLCG2 in cancer are still lacking." (PMID 33282950, 2020).
infection (1 paper, 2025). The state of being infected such as from the introduction of a foreign agent such as serum, vaccine, antigenic substance or organism. "Most surprisingly, SGPP2, encoding a second S1P phosphatase was markedly upregulated upon Ctr infection (log2 fold change = 4.1)." (PMID 40249190, 2025). "P < 0.05), we believe that SGPP2 could play a fundamental role in attenuating intracellular S1P signaling during Ctr infection of M2Φ." (PMID 40249190, 2025).
SGPP2 also shares sentences with these, for which no sentence is quoted: atopic dermatitis (1 paper); Atrophy (1); chronic endometritis (1); Chronic Heart Failure (1); colorectal cancer (1); COVID-19 (1); depression (1); ischemic cardiomyopathy (1); liver cancer (1); lung adenocarcinoma (1); lung carcinoma (1); malignant glioma (1); muscular atrophy (1); Myocardial fibrosis (1).